KRAS (KRas proto-oncogene, GTPase)
Diseases named in the same sentence as KRAS in open-access papers (continued):
Sharing a sentence is not in itself a finding about the gene and the disease.
tumor (continued). "Recently, our group reported that KRAS alteration and chromosomal instability were associated with resistance to PD-1/PD-L1 blockade immunotherapy, whereas high intratumoral tumor-infiltrating lymphocyte density was associated with a favorable immunotherapy response in patients with CCA." (PMID 35433771, 2022). "Additionally, we studied the association of KRAS expression levels with diagnostic and prognostic values, clinicopathological features, and tumor immunity." (PMID 36330448, 2022). "BRAF mutation was present in 25% and KRAS mutation in 37% of patients’ tumours." (PMID 35574322, 2022). "To further explore the relationships between clinical variables and mRNA expression of ATG2B in CRC tissues, we chose the characteristics of tumor stages, metastasis, sex, age, family history, tumor site, BMI, and KRAS mutation status for analysis in TCGA datasets." (PMID 35992821, 2022). "Moreover, in agreement with previous findings in other tumor types harboring oncogenic KRAS mutations, we also found that KRASG12D can promote IL6 expression in CCA cells." (PMID 35619118, 2022). "Therefore, a KRAS G12C mutation is noted in around 1% of patients showing tumor progression after first-line treatment with TKIs." (PMID 35406400, 2022). "Both frozen or FFPE (formalin-fixed, paraffin-embedded) tumor tissue as well as stool samples from patients with benign and malignant pancreatic diseases were analyzed by PCR, phage cloning and plaque hybridization assay for KRAS codon 12 mutations." (PMID 35625579, 2022). "In the subset of patients whose tumor harbored a KRAS G12C mutation (N = 30, 37% of all KRAS tumors), encouraging outcomes were also observed for the addition of ICI to chemotherapy with a PFS HR of 0.51 (95% CI: 0.21–1.21; p = 0.120) and an OS HR of 0.56 (95% CI: 0.20–1.56; p = 0.264)." (PMID 36426286, 2022). "A total of 225 patients enrolled in the IMpower150 trial had a KRAS mutation in their tumor." (PMID 36426286, 2022). "They found that high expression levels of ERBB2 occurred in spheres showing hyperactive PI3K/AKT pathway and proved that triple targeting of ERBB2, MEK and PI3K induces CSC death and regression of anti-EGFR-resistant tumor xenografts, including those carrying KRAS and PIK3CA mutation." (PMID 35582524, 2022). "Interestingly, recent studies also indicate the association between KRAS mutation and anti-tumor immunity." (PMID 35327394, 2022). "PAT8 presented KRAS p.G12D mutated in the primary tumor and wild-type KRAS in the liver metastasis." (PMID 35936004, 2022). "Moreover, there are several reports linking KRAS mutations with enhanced PD-L1 expression on tumor cells, which results in reduced T cell functionality." (PMID 35205776, 2022). "Mutated KRAS in combination with inflammation or loss of key tumor suppressors drives progression of pre-malignant lesions to PDAC and is implicated in the recruitment of an immunosuppressive cellular milieu through KRAS-driven production of pro-inflammatory cytokines and chemokines." (PMID 36077755, 2022). "Overall, KRAS mutations induce autophagy to promote survival and tumor progression." (PMID 35883626, 2022). "The same KRAS mutation has been observed by a few studies in both tumor lines." (PMID 36309754, 2022). "Likewise, KRAS downstream effects have been reported to be context-dependent, showing allele and tissue/tumor specificities." (PMID 35805073, 2022). "PDAC is a tumor driven by KRAS mutation, which explained its striking prevalence of over 94%." (PMID 35180847, 2022).
tumor (continued). "KRAS mutation-positivity within the resection margins indicates that tumours cells may persist after resection." (PMID 35194118, 2022). "While mutated KRAS reportedly is leading to increased ROS generation and tumor promotion, elevated ROS levels may also trigger tumor cell death." (PMID 35158942, 2022). "Furthermore, previous study had shown that ICIs inhibited more effectively the tumor progression in NSCLC patients with KRAS mutations compared with ALK rearrangements." (PMID 36159860, 2022). "Intriguingly, more DEGs between KRASG12V and KRASWT were identified for actively dividing tumor cells, which suggested that KRAS mutations may mainly affected tumor cells that were actively dividing." (PMID 35974387, 2022). "In cancer cells, KRAS mutations are able to influence the expression levels of a diversity of proteins involved in apoptosis regulation and can also stimulate autophagy in order to favor cell survival and tumor progression." (PMID 35883626, 2022). "Also, two investigations showed that KRAS mutations were associated with exposure to smoky coal; based on the mutation spectra in tumor genes, the gene mutation can be attributed to direct DNA damage from mutagenic exposures." (PMID 35991047, 2022). "The patients with KRAS mutations at the Q61 site had on average 6.6 copies of the neoantigen present on each tumor cell surface, and the neoantigens flanking the G12 site had an average of 32.1 copies present per tumor cell." (PMID 35267551, 2022). "Our results indicate that the mutational status of KRAS could partially explain why tumor organoids are more sensitive to sorafenib treatment than healthy organoids." (PMID 36429040, 2022). "The first is the early diagnosis as one can imagine that circulating tumor cells that present significantly higher KRAS mutations than those found in biopsies from the primary tumor could evidence higher risk for BM." (PMID 35482170, 2022). "Importantly, these KRAS-linked metabolic reprograming features differ according to KRAS copy number, tumor types, and genetic context." (PMID 35681624, 2022). "RNF43 inactivating mutation and KRAS activating mutation coexist in a subset of IPMN tumor tissues." (PMID 35229994, 2022). "A KRAS G13C mutation was also identified in this patient’s tumor molecular data." (PMID 35949786, 2022). "Then, the expression levels of ZNF24 and SLC7A5 were detected in 16 selected KRAS mutation tumor tissues and KRAS wild-type tumor tissues from the samples by qPCR and Western blot analysis, and we found that the expression levels of ZNF24 and SLC7A5 were both increased in KRAS mutation patients." (PMID 36505791, 2022). "The SMAD4-p.His530ThrfsTer47 and KRAS-p.Gly12Val mutation might promote the occurrence and distant metastasis of the tumor." (PMID 35299731, 2022). "However, a larger study with 58 patients did find discordance in 42% of patients where a different KRAS mutation was found compared to their primary tumor." (PMID 35163592, 2022). "Interestingly, the 24-month PFS rate was higher for patients with KRAS mutated tumours compared to BRAFwt/KRASwt tumours, reaching 87.5% (95% CI, 38.7 to 98.1) and 68.4% (95% CI, 35.9 to 86.8), respectively." (PMID 35574322, 2022). "However, KRAS inhibitors are being explored in several tumor types since KRAS mutations are among the most frequent genomic alterations causing cancer." (PMID 36010306, 2022). "While mutation of KRAS was a rare event in RCC, wild type KRAS could exert tumor suppressor effects on RCC cell proliferation and tumor growth." (PMID 35356208, 2022). "The oncogene KRAS is associated with tumor development and drug resistance." (PMID 36230574, 2022).
tumor (continued). "KRAS mutations in PDAC are known to act as the driver for tumor formation." (PMID 35159117, 2022). "KRAS expression was significantly associated with histological tumor grade, tumor extent, presence of nodal and distant metastasis, pathological stage, and the presence of lymphovascular invasion (P=<0.001, 0.001, 0.001, 0.009, <0.001, and <0.001, respectively)." (PMID 36532636, 2022). "Moreover, MET PET parameters showed significant associations with tumor location, sex, KRAS variant, and symptoms." (PMID 35130327, 2022). "According to this result, the KRAS G12D mutation could be proposed as a high-grade tumor budding biomarker." (PMID 35096426, 2022). "Moreover, a nomogram was constructed to predict 1-, 2-, and 3-year OS probability among individuals with LUAD, which comprised clinical features of age, gender, tumor stage, KRAS status and prognostic risk score model." (PMID 36612054, 2022). "The earliest study we found aimed at testing whether KRAS mutations present in tumor cells that were shed into exocrine pancreatic secretions of PDAC patients could also be detected in stool." (PMID 35625579, 2022). "The relationship between KRAS mutation and tumor budding has previously been reported." (PMID 35096426, 2022). "Here, we took advantage of the whole-genome CRISPR knock-out screening to analyze whether, several genes involved in ferroptosis are differentially required in tumor cells having mutations in the RAS genes (KRAS, NRAS and HRAS) and those harboring KRAS-WT." (PMID 35912247, 2022). "Preclinical and clinical data on the targeting of this pathway in KRAS mutant tumors indicate that combination treatment of immunotherapies with allele-specific RAS inhibitors might enhance the anti-tumor efficacy of immunotherapy in RAS-mutant tumors." (PMID 35456940, 2022). "We defined KRAS G12D mutation as a biomarker of high-grade tumor budding." (PMID 35096426, 2022). "In addition, KRAS mutations are known to induce autophagy in order to promote cell survival and tumor progression through MAPK and PI3K regulation." (PMID 35883626, 2022). "The most frequent variant in our group was EGFR L858R, detected in 5 out of 26 (19.23%) plasma samples and in 3 out of 26 (11.53%) tumor samples, followed by the group of variants detected in codon 12 of KRAS gene (4 out of 26 or 15.38%) in plasma and tumor tissue." (PMID 36551569, 2022). "On the other hand, the L6 tumor had KRAS mutation, which is typical of CMS3." (PMID 35837106, 2022). "Activating KRAS mutations were found in 31/77 examined tumor cases (40.3%)." (PMID 35096426, 2022). "Already, clinical trials testing the efficacy of MET inhibitors in METΔexon14-presenting tumours have identified amplification and/or activating mutations in the KRAS or BRAF genes (as well as activating mutations in the PI3K-AKT pathway) to be a common form of acquired resistance." (PMID 35326531, 2022). "Molecular analysis of the tumor tissue showed a KRAS-splice-site mutation (c451-3C > T)." (PMID 35401087, 2022). "Our recent results, taken together with relevant studies reviewed above, raise the question of whether KRAS pathway mutations are early tumor-initiating or late subclonal events during MPM evolution." (PMID 36077838, 2022). "Tumors with high-grade tumor budding were strongly associated with KRAS G12D mutation (P=0.007)." (PMID 35096426, 2022).
tumor (continued). "In conclusion, in these real-life and population-based cohorts reflecting the background population, we did not detect any significant or clinically relevant differences in patient characteristics and tumor outcomes between patients with KRAS-G12C tumors compared to those with other KRAS mutations." (PMID 35251991, 2022). "A descriptive post hoc analysis from KEYNOTE 189 identified 89 patients with a KRAS-mutated tumor." (PMID 36426286, 2022). "However, KRAS mutations are correlated with an inflammatory tumor microenvironment and tumor immunogenicity, resulting in superior patient response to PD-1/PD-L1 inhibitors." (PMID 35582531, 2022). "KRAS mutations can control various aspects of the tumor microenvironment." (PMID 35883598, 2022). "One study included 160 patients with a known KRAS mutation in tumor tissue." (PMID 35565347, 2022). "Recently, it has been identified that braf and myc oncogenes are responsible for the kras-driven PDAC and are linked to the immunomodulatory effect of KRAS, which is responsible for upregulating M2 macrophage infiltration into tumor sites and for reduced numbers of CD4+ and CD8+ lymphocytes." (PMID 35008414, 2022). "Therefore, KRAS mutation in CRCs is associated with more reduced survival, increased tumor aggressiveness, and resistance to anti-epidermal growth factor receptor (EGFR) targeted-therapies." (PMID 35562390, 2022). "The low detection rate of KRAS mutations in tumor tissue (77%) and the relatively low frequency of the mutated alleles might reflect the lower mutational burden in the surgically resected samples after NAT." (PMID 36232820, 2022). "The main elements which define the variability in the TME includes but are not limited to genomic instability, tumor type, tumor location, presence of mutations such as KRAS, EGFR, PTEN etc., presence of lymph nodes, adipose tissue in the vicinity, and therapeutic interventions." (PMID 36253762, 2022). "Because FTCs or PTC cases harboring NRAS or KRAS mutations exhibit the maximum tumour shrinkage, the tumour genotype may represent a predictor of response to cabozantinib." (PMID 35408830, 2022). "Indeed, although the tumor type is driven by KRAS mutations, its codons and the frequency of mutations vary by tissue type." (PMID 35922812, 2022). "This information may have significant impact on operation of clinical trials in rare tumor patients with KRAS mutation in China." (PMID 35359599, 2022). "In the same way, molecular detection of KRAS mutations within the venous margins of the resected tumour may indicate tumour cell dissemination." (PMID 35194118, 2022). "Univariate analysis of factors correlated with OS and DFS in PDAC patients showed that age, TNM stage, T stage, N stage, tumour differentiation, resection margin, presence of KRAS mutation, and presence of KRAS wild-type were associated with OS of PDAC patients (P < 0.05)." (PMID 36582783, 2022). "Tumor biology and drug sensitivity change with the site of the KRAS and BRAF mutations." (PMID 35280113, 2022). "Recent meta-analysis have shown mutation status and tumour sidedness may impact survival and disease progression; KRAS mutations present in 35% of left sided and 46% of right sided tumours." (PMID 36358810, 2022).
tumor (continued). "KRAS promotes the initiation of tumor growth and ensures tumor progression by stimulating tumor-associated angiogenesis and activating different effector pathways through the upregulation of VEGF (vascular endothelial growth factor) and CXC chemokine interleukin-8 (IL-8)." (PMID 36077640, 2022). "KRAS co-occurring mutations are critical factors dictating ICIs tumor response." (PMID 35406531, 2022). "Loss of BCL9/9L accelerates differentiation and delayed tumour growth in APC or KRAS tumours." (PMID 35815339, 2022). "Among the ones reported, her tumor harbored a KRAS G12R mutation." (PMID 34915443, 2022). "Among the 17 studies, 13 (76.5%) used FFPE tumor samples for KRAS, NRAS and BRAF mutation analysis." (PMID 36344948, 2022). "Currently, the first-line treatment in daily practice of patients with KRAS-mutated tumors associates ICIs (pembrolizumab) and chemotherapy or immunotherapy (pembrolizumab) alone for tumors expressing PD-L1 in more than 50% of tumor cells." (PMID 35406400, 2022). "Namely, comparing the known KRAS mutations to the different mutation signatures present in each tumor revealed that while most oncogenic KRAS mutations tracked to the dominant mutation signature of each tumor, nearly a quarter of the KRASG12/13C mutations tracked with a minor mutation signature." (PMID 35482806, 2022). "Oncogenic KRAS has also been implicated in tumor immune evasion." (PMID 36077755, 2022). "The KRAS G12C mutation can co-occur with other genetic alterations that are not targeted by the inhibitor molecule, which could continue to promote tumor growth and treatment resistance." (PMID 35205778, 2022). "Interestingly, successful immune enrichment of tumor sEVs has been shown as a proof-of-concept study in PDAC patients for the analysis of KRAS mutations by ddPCR; however, further optimization is still required prior to clinical implementation." (PMID 35205822, 2022). "The absence of this effect in A549 cells could be due to the activating mutation in the KRAS gene, which in turn could limit the tumor suppressor effect of miR-17-5p, independently activating cell proliferation." (PMID 35884472, 2022). "Round shape, nodules in non-tumour lobes, and smoking were variables linked to KRAS mutation." (PMID 35406429, 2022). "Furthermore, K147 acetylation regulates nucleotide binding and is associated with increased KRAS activity and tumor growth in vivo." (PMID 36334633, 2022). "Furthermore, 90% of advanced PDAC tumor present KRAS mutations impacting in several oncogenic signaling pathways, many of them associated with cell proliferation and tumor progression." (PMID 35684434, 2022). "The challenge in PDAC is its enormous therapy resistance due to the evolution of aggressive cancer cells driven by oncogenic KRAS and loss of key tumor suppressors in a complex adapting microenvironment with various signaling effectors and biophysical and hypoxic restraints." (PMID 36494842, 2022). "In addition,KRAS mutation has been found in approximately 30% of all human cancers and is assumed to play a critical role in tumor occurrence and progression, which further explains the applicability and generalizability of the positive-feedback loop." (PMID 36017891, 2022). "His tumor was pMMR by IHC and harbored a KRAS G12L mutation." (PMID 34991708, 2022). "KRAS mutations were found in all tumor types except for G-type tumors." (PMID 35778698, 2022). "In summary, our results show that co-occurring KRAS mutations exist in up to 8% of KRAS c.34G>T-positive NSCLC tumours, with KRAS c.35G>T being the most frequent and translating to either G12F or G12C & G12V double mutant, when occurring in cis or trans respectively." (PMID 35177674, 2022).